MAP2K4 (mitogen-activated protein kinase kinase 4)
Diseases named in the same sentence as MAP2K4 in open-access papers (continued):
Sharing a sentence is not in itself a finding about the gene and the disease.
prostate carcinoma (21 papers, 2010 to 2024). A carcinoma that arises from epithelial cells of the prostate gland. "Studies in prostate cancer demonstrated that overexpressed MAP2K4 promotes prostate cancer metastasis through HSP27 upregulation, which mediates MMP-2 upregulation." (PMID 31761784, 2019). "Mechanistically, PAGE4 promoted the survival of prostate cancer cells through regulating MAPK pathway which reflected in decreasing the phosphorylation of MAP2K4, JNK and c-JUN but increasing phosphorylation of ERK1/2." (PMID 30658679, 2019). "The uncertainty of MAP2K4's role in regulating human prostate cancer metastasis is further increased by studies across several different cancer types which support either a metastasis suppressor, or stimulatory role." (PMID 25019290, 2014). "Importantly, MAP2K4 has been demonstrated to be a direct activator of MAP kinases that promote human prostate cancer metastasis and act as prognostic markers of osteosarcoma tumorigenesis." (PMID 32014061, 2020). "In addition, MAP2K4 activates p38 protein to induce the transformation of prostate cancer epithelial cells into mesenchymal cells, which results in distant tumor cell metastases." (PMID 31761784, 2019). "Genistein could bind to and inhibit mitogen-activated protein kinase kinase 4 (MEK4) kinase activity in prostate cancer cells, which in turn attenuated matrix metalloproteinase-2 (MMP-2) expression and reduced cell invasion." (PMID 29743815, 2018).
lung carcinoma (20 papers, 2013 to 2025). "Lobectomy for lung cancer would result in a dramatic increase in stress and pro-inflammatory signals that activates MAP2K4 and signaling through the MAPK stress pathway." (PMID 26165383, 2015). "Both MAP2K4 and NRP1 are well known to be associated with lung cancer." (PMID 24669769, 2014). "In lung cancer, overexpression of LncRNA PCAT19 increased apoptosis in cancer cells through miR‐25‐3p/MAP2K4 signaling axis." (PMID 36992525, 2023). "Concurrent expression of dominant-negative mitogen-activated protein kinase kinase 4 (MKK4) and PI3K p85α isoform is also synergistic to induce apoptosis in lung cancer." (PMID 27176481, 2016). "Very recently, the KRASG12C inhibitor sotorasib and the MAP2K4 inhibitor HRX-0233 were shown to synergistically inhibit growth of a number KRAS mutant CRC and lung cancer cell lines and to induce durable tumor shrinkage in mouse xenografts of human lung cancer cells." (PMID 40419504, 2025). "Additionally, genes involved in the MAPK signaling pathway include BRAF, c-Jun, ERK, JNK, MAP2K1, MAP2K4, MAPK14, and KRAS, which are genes affected by MPs in lung cancer cells." (PMID 41378310, 2025). "This suggests that the effect of MAP2K4 variation is in the immediate post-operative state and not the long term effect of lung cancer." (PMID 26165383, 2015).
ovarian carcinoma (16 papers, 2010 to 2025). A malignant neoplasm originating from the surface ovarian epithelium. "Several studies have reported somatic mutations in the MAP2K4 gene in multiple cancer types including ovarian cancer." (PMID 22355333, 2012). "In summary, we have conducted a comprehensive analysis of mutation, methylation, expression and gene knockdown of MAP2K4 in ovarian cancer." (PMID 21575258, 2011). "Conversely, the reduced expression of the MAP2K4 protein in tumor tissues reinforces its recognized function as a tumor suppressor, consistent with earlier findings in ovarian cancer." (PMID 41515982, 2025). "In ovarian cancer, in addition to the apparent role of MAP2K4 in metastasis suppression, there have been limited data showing loss of expression and genetic aberrations in several small cohorts." (PMID 21575258, 2011). "Despite this accumulating evidence, the status of MAP2K4 as a tumor suppressor in ovarian cancer is equivocal and therefore in this study we have undertaken a comprehensive analysis of mutation, methylation and gene knockdown." (PMID 21575258, 2011). "MAP2K4 is targeted by genetic inactivation in ovarian cancer and restricted to high grade serous and endometrioid carcinomas in our cohort." (PMID 21575258, 2011). "We did find genetic alterations confirming MAP2K4 as a tumour suppressor gene for ovarian cancer in a subset of high grade serous and endometrioid cases, including a specific 16 bp homozygous deletion in exon 7 as well as larger homozygous deletions." (PMID 21575258, 2011). "In terms of tumor-suppressor genes, MAP2K4 inactivation was confirmed in ovarian cancer cell lines." (PMID 34857007, 2021). "In addition, we found that MAP2K4 was frequently targeted by hemizygous deletion and that this correlated with decrease in gene expression in several independent ovarian cancer data sets." (PMID 21575258, 2011). "In ovarian cancer, MAP2K4 overexpression inhibits NF-κB phosphorylation and up-regulates E-cadherin expression in epithelial cells to inhibit EMT in ovarian cancer." (PMID 31761784, 2019). "Analysis of a number human ovarian cancer cell lines showed that MAP2K4 expression is not detectable in 3 cell lines (SHOV3ip.1, SKOV-3 and HEY-A8) known to be metastatic in vivo while other members of the MAP2K4 pathway are intact including MEKK1, MKK7, JNK and c-JUN." (PMID 22355333, 2012).
pancreatic cancer (15 papers, 2007 to 2025). "In a pancreatic cancer cell line, MAP2K4 mapped with the D17S969 marker, which is located in a region of high incidence of LOH in multiple cancers." (PMID 30548122, 2019). "More recent studies have confirmed these findings, showing that MAP2K4 genetic inactivation is prevalent in high grade serous and endometrioid carcinomas, breast cancer, and pancreatic cancer." (PMID 26894955, 2016). "Both MAP2K4 and GNAS are known to be involved in pancreatic cancer [Cancer Gene Census and Intogen databases]." (PMID 28473845, 2017). "Further studies of the potential dual role of MAP2K4 and GNAS might help elucidating the molecular basis for the complex bidirectional relationship observed between diabetes and pancreatic cancer." (PMID 28473845, 2017).
colorectal cancer (9 papers, 2010 to 2025). A primary or metastatic malignant neoplasm that affects the colon or rectum. "Furthermore, deletions and mutations of the MAP2K4 have been described in human pancreatic, lung, breast, testicle, and colorectal cancer cell lines, suggesting a tumor suppressor role." (PMID 24391818, 2013). "Losses in 18q21.2, 5q21.1, and 17p12 loci were associated with reduced protein levels of three important colorectal cancer drivers: SMAD4; APC; and MAP2K4, respectively (FDR < 0.1)." (PMID 28854368, 2017). "MAP2K4 has previously been reported to be over-expressed in pancreatic, breast and colorectal cancer, while LHFP expression has been reported in lipomas." (PMID 24194916, 2013). "Reduced MAP2K4 gene expression results in decreased production of the kinase needed by the MAPK signaling pathway to stimulate apoptosis and hence a poor prognosis in colorectal cancer." (PMID 41515982, 2025). "In addition, FHOD3 and MAP2K4 were previously defined as candidate cancer genes (CAN gene) by integrated analysis of homozygous deletions and sequence alterations in breast and colorectal cancers." (PMID 21108794, 2010).
glioblastoma (8 papers, 2015 to 2025). The most malignant astrocytic tumor (WHO grade IV). "It has been shown that MAP2K4/MKK4 is important for induced vacuolization of glioblastoma cells, which might be associated with the two classical features of HHV‐6B infection that are change in cell morphology and vacuolization of cells." (PMID 33037649, 2020). "Another gene whose expression level correlated positively with resistance to three types of glioblastoma treatment was mitogen-activated protein kinase kinase 4 (MAP2K4)." (PMID 36906590, 2023). "It was reported that ZDHHC17 was upregulated in glioblastoma multiforme (GBM) and contributed to GBM malignant development through promoting MAP2K4 and P38/JNK activation." (PMID 35297315, 2022). "Furthermore, it can participate in palmitoylation-independent functions, such as interaction with MAP2K4 to activate JNK/p38 and regulate malignant glioblastoma multiforme development and progression." (PMID 34700373, 2021).
osteosarcoma (8 papers, 2008 to 2022). A usually aggressive malignant bone-forming mesenchymal neoplasm, predominantly affecting adolescents and young adults. "We also observed downregulation of Map2k4, which has been shown to be overexpressed in osteosarcomas and associated with a poor response to treatment, tumor progression, and worse overall survival." (PMID 29108266, 2017). "Our results are in line with the finding of Pan and colleagues’ that miR-27a inhibits JNK/p38 expression by targeting MAP2K4 mRNA at its 3′-UTR in human osteosarcoma cells." (PMID 29375563, 2017).
Cerebral ischemia (7 papers, 2012 to 2024). Restriction of arterial blood supply to the brain associated with insufficient oxygenation to support the metabolic requirements of the tissue. "MAP2K4 as the direct upstream activator of NH2-terminal kinase pathway, which plays an important role in regulating neuron survival and apoptosis in response to cerebral ischemia." (PMID 33445426, 2021).
glioma (7 papers, 2018 to 2024). A benign or malignant brain and spinal cord tumor that arises from glial cells (astrocytes, oligodendrocytes, ependymal cells). "ZDHHC17 and MAP2K4 expression was markedly enhanced in mesenchymal GSCs, which are closely associated with post-radiation or chemotherapeutic glioma recurrence." (PMID 31938047, 2020). "Expression of both ZDHHC17 and MAP2K4 was progressively elevated in glioma samples from grade I to grade IV versus normal brain tissues, and was highly correlated." (PMID 31938047, 2020). "Next, we checked ZDHHC17 and MAP2K4 expression in a glioma tissue microarray (TMA) by immunohistochemistry." (PMID 31938047, 2020). "Overall, the present study showed that ZDHHC17 was up-regulated in glioma as compared to normal brain tissue, and that it recruited MAP2K4 and JNK/p38 to build a signaling module for JNK/p38 activation in GBM." (PMID 31938047, 2020). "Further studies implied that MAP2K4-ZDHHC17-JNK/p38 forms a signaling module for JNK/p38 activation in glioma, including gliomagenesis and malignant progression." (PMID 31938047, 2020). "Our results indicated that ZDHHC17 recruits JNK/p38 and MAP2K4 to form a signaling module for JNK/p38 activation during glioma progression and malignant development." (PMID 31938047, 2020). "In the following manuscript, we provide new and unprecedented evidence of a significant role of miR-744 in the regulation of its host gene MAP2K4 in human glioma." (PMID 30366472, 2018). "ZDHHC17 over-expression could help maintain glioma cell stemness because the upregulation of the SOX2-positive cell population, whereas MAP2K4 knockdown or genistein treatment suppressed glioma stem cell (GSC) self-renewal." (PMID 31938047, 2020). "However, other ZDHHCs, such as ZDHHC17, have been found to accelerate glioma progression by interacting with MAP2K4, and this function may depend on the ZDHHC17 ankyrin-repeat domain, rather than its palmitoyltransferase activity." (PMID 37161425, 2023). "MKK4 acts as a tumor suppressor, and upregulation of MAP2K4 activates the JNK signaling pathway to promote the growth of glioma cells." (PMID 39691419, 2024). "Although ZDHHC17 and MAP2K4 staining intensities varied among the untreated glioma tissues, ZDHHC17 and MAP2K4 expression tended to increase in recurrent compared to naive tumor sections (4 of 5)." (PMID 31938047, 2020). "Both western blotting and RT-PCR results indicated that MAP2K4 and ZDHHC17 were increased in the glioma spheres after 6 Gy radiation or TMZ treatment, similar to EZH2 expression." (PMID 31938047, 2020). "Attesting to its specificity, the expression of ZDHHC13, the homeodomain protein of ZDHHC17, was not related to MAP2K4 expression in glioma tissue." (PMID 31938047, 2020). "Kaplan-Meier survival analysis showed that patients with highly ZDHHC17- expressing glioma had shorter disease-free survival (DFS) and OS than the low-expression groups; similar results were also obtained for patients with highly expression of MAP2K4." (PMID 31938047, 2020). "Inhibition of TGFB1 by miR-744 thus fulfills a dual role in mediating effects of this intronic miRNA on its host MAP2K4: (i) Functional antagonization via blocking SMAD-signaling, thereby reducing glioma migration and invasion; and (ii) control of the tumorigenic host’s expression levels." (PMID 30366472, 2018). "Moreover, the gene encoding ZDHHC17 is located in the chromosomal region containing a potential oncogene for glioma and ZDHHC17 protein can interact with MAP2K4 to regulate the development and progression of malignant glioma and stimulate JNK/p38 (our unpublished data)." (PMID 30658672, 2019).
hepatocellular carcinoma (7 papers, 2014 to 2025). A malignant tumor that arises from hepatocytes. "In AEG-1-C75S liver, activation of cell proliferation and invasion were detected which were associated with activation of oncogenic MAP2K4, MAP3K1, TGFA, NRF2, and STAT3 signaling ultimately contributing to hepatocellular carcinoma." (PMID 38677511, 2024).
lung adenocarcinoma (7 papers, 2015 to 2022). A carcinoma that arises from the lung and is characterized by the presence of malignant glandular epithelial cells. "Besides, MAP2K1 and MAP2K4 mutations can be related with MAPK pathway activity as identified in the TCGA lung adenocarcinoma original article." (PMID 32998690, 2020). "Ahn and coworkers identified mitogen-activated protein kinase kinase 4 (MAP2K4) as a tumor suppressor in lung adenocarcinoma." (PMID 35954274, 2022). "Studies of lung adenocarcinoma found that MAP2K4 overexpression inhibits tumor cell invasion by down-regulating PPARγ2, showing that MAP2K4 acts as a tumor suppressor gene in tumor progression." (PMID 31761784, 2019).
breast tumors (6 papers, 2014 to 2022). "The sequencing of breast tumor genomic DNA has revealed mutations in genes that encode members of this pathway, including MAP3K1, MAP2K4, and MAP2K7." (PMID 29856313, 2018). "Moreover, JNK signaling is also inhibited by phosphorylation of MAP2K4 by AKT in breast tumors with AKT activation caused by ‘driver’ mutations in PTEN or PIK3CA." (PMID 29856313, 2018).
epilepsy (6 papers, 2020 to 2025). A brain disorder characterized by episodes of abnormally increased neuronal discharge resulting in transient episodes of sensory or motor neurological dysfunction, or psychic dysfunction. "The complex regulatory associations between genes such as RPS6KA3 and MAP2K4 and multiple miRNAs highlight that these miRNAs may play essential roles in the pathological process of epilepsy by regulating gene expression." (PMID 40520613, 2025). "According to the ROC curves, the expression level of key genes including CTSD, CREG1, PECAM1, ZNF101, RRM2B, MARCKSL1, and MAP2K4 demonstrated a certain accuracy in classifying epilepsy and control groups (0.7 < AUC < 0.9)." (PMID 40520613, 2025). "Early identification of high-risk epilepsy patients can help with personalized treatment strategies by detecting expression levels of key genes, including ZNF101 and MAP2K4." (PMID 40520613, 2025). "Upregulating the expression of MAP2K4 in epilepsy can inhibit inflammatory response and hippocampal neuronal apoptosis;50 Paeoniflorin inhibits the apoptosis of hypothalamic neurons by inhibiting the MKK4‐JNK signaling pathway." (PMID 39691419, 2024). "In contrast, the inhibition of miR-27a-3p prevented epilepsy-induced inflammatory responses and hippocampal neuronal apoptosis by targeting mitogen-activated protein kinase 4 (MAP2K4) in the same model of TLE." (PMID 38525737, 2024). "Previous preliminary experiment data and other research results showed that miR-27a-3p inhibitors prevented epilepsy-induced inflammatory responses and hippocampal neuronal apoptosis by targeting MAP2K4." (PMID 35422840, 2022). "miR-27a-3p downregulation in rats was also linked to the upsurge of mitogen-activated protein kinase 4 (MAP2K4) production, resulting in a suppression of hippocampal neuronal apoptosis in epilepsy, both in vivo and in vitro." (PMID 34199498, 2021). "Recently, the downregulation of miR-27a-3p suppressed inflammatory response and apoptosis of hippocampal neuronal cell in epilepsy via increasing mitogen-activated protein kinase 4 (MAP2K4)." (PMID 32528555, 2020). "ZNF101 may influence neuronal survival by regulating DNA repair or apoptosis, while MAP2K4 is involved in the pathogenesis of epilepsy by affecting apoptosis and inflammation through the MAPK signaling pathway." (PMID 40520613, 2025). "Notably, ZNF101 and MAP2K4 significantly contribute to epilepsy diagnosis." (PMID 40520613, 2025). "MAP2K4 regulates the JNK and p38 MAPK pathways, impacting stress, apoptosis, and inflammation, and plays an important role in epilepsy-related neuronal damage and chronic inflammation." (PMID 40520613, 2025). "Abnormal MAP2K4 expression may worsen neuronal stress and inflammation through JNK and p38 pathways, highlighting its role in epilepsy." (PMID 40520613, 2025).
colon cancer (4 papers, 2016 to 2025). "A study on the role of miRNA molecules in regulating the MAP2K4 suppressor gene found that inhibition of its expression promotes the proliferation of colon cancer cells." (PMID 41515982, 2025). "For the top colon cancer MEGs, the consistent tumor suppressor genes included MAP2K4, MAPK10, RUNX3, WNK2 (the four genes were identified by the TSGene 2.0 database), BECN1, FASN, NAT1, and NR3C2." (PMID 33273919, 2020). "Similar results were found for MAP2K4 knockout LoVo and DLD1 colon cancer cells." (PMID 29795445, 2018).
diabetes (4 papers, 2017 to 2020). "Durable epigenetic modifications are programmed by maternal overnutrition—in C57BL6/J mice, hepatic insulin receptor substrate 2 (Irs2) and mitogen-activated protein kinase 4 (Map2k4) gene methylation occurred in progeny, thereby increasing their susceptibility to diabetes." (PMID 33158303, 2020).
gastric cancer (4 papers, 2014 to 2020). A primary or metastatic malignant neoplasm involving the stomach. "Interestingly, mutations in MAP3K1/MAP2K4 are more prevalent in breast, prostate, and stomach cancer, and less common in other types of cancers." (PMID 32886682, 2020).